CCND1 (cyclin D1)
Diseases named in the same sentence as CCND1 in open-access papers (continued):
Sharing a sentence is not in itself a finding about the gene and the disease.
cancer (continued). "Cell cycle dysregulation caused by aberrant cyclin D1 and CDK4 expression is a major determinant of cancer cell proliferation in MCL." (PMID 37225761, 2023). "Cyclin D1 is overexpressed in various types of cancers; however, findings on its prognostic impact remain inconclusive." (PMID 37894399, 2023). "In an animal model, TH revealed chemopreventive properties by decreasing cancer cell proliferation and activity, as seen by a reduction in the expression of cancer-related genes such as CCND1, EGFR, and COX-2." (PMID 36830249, 2023). "Therefore, the G870A mutation of CCND1 may be a key risk factor for cancers." (PMID 37024471, 2023). "G1 arrest accompanying decrease of CKD6, cyclin A and cyclin D1 have been demonstrated in most human cancer cell lines exposed to monensin." (PMID 36896461, 2023). "Antileukoproteinase 1 increases the expression of cyclin D1 gene, decreases the tumor-suppressor gene lysyl oxidase, and protects progranulin, a highly expressed factor in aggressive cancers, from proteinase degradation." (PMID 36742380, 2023). "The isoforms of CCND1 had been deemed to contribute to the invasion and metastasis of various human cancers." (PMID 37024471, 2023). "CCNA2 has an important role in promoting G1-S cell cycle progression by facilitating CCND1 regeneration and participating in processes such as chromosome instability, cancer cell function, and cell maturation." (PMID 37853361, 2023). "These LN-FLU cells displayed characteristics of cancer stem cells, exhibited drug resistance, and showed a significantly reduced expression of Cyclin D1, along with the overexpression of p16, pointing to a proliferation arrest." (PMID 37958610, 2023). "The amplification and/or overexpression of CCND1 have frequently been found in a variety of cancers." (PMID 37024471, 2023). "The β-catenin that accumulates in the nucleus interacts with TCF/LEF and activates the expression of target genes, including c-Myc, VEGF, and cyclin D1, to promote the genesis of cancers." (PMID 37763649, 2023). "The anti-cancer effect of niclosamide was mediated by the downregulation of the Wnt/β-catenin signaling, which downregulated β-catenin, Cyclin D1, DVL2, and p-GSK3β proteins in the ALDH+ treated cells." (PMID 38170015, 2023). "In cancer cells, Pxn phosphorylation is regulated by the kinase activity of Cdk4 and by the cytoplasmic Ccnd1, which colocalize with FA components, thus regulating cell invasion and metastasis." (PMID 37373242, 2023). "Genes involved in endocrine resistance pathways primarily fell into 3 functional categories: ERBB2/IGF1R, CCND1, and BCL2, which have been reported to be associated with endocrine resistance and an increased risk of cancer recurrence in breast cancer." (PMID 37328469, 2023). "First, we observed that DVL2 directly regulates expression of genes involved in cancer hall marks, CCND1, VEGFA and POU5F1." (PMID 36809986, 2023). "Although a lot of studies have shown that CCND1 subtype is related to the invasion and metastasis of cancer cells, how CCND1 isoforms regulate invasion and metastasis independently from the cell cycle still needs to be further explored." (PMID 37024471, 2023). "Formononetin showed inhibitory activity against cancer cells in vivo and in vitro, which is connected to G1 cell cycle arrest by the inactivation of Akt/cyclin D1/CDK4." (PMID 37298670, 2023). "A great deal of study has indicated that dysregulated expression of CCND1 isoforms affect the multiple hallmarks of cancer." (PMID 37024471, 2023). "Cyclin D1 has been shown to be frequently up-regulated in many different cancer types and its up-regulation triggers tumorigenesis through induction of transcription, translation, and protein stability." (PMID 36849756, 2023).
cancer (continued). "S.M 50%EE treated HepG2 and Caco-2 cell lines significantly downregulated Cyclin D1 expression level by more than five folds in HepG2 cancer cells and by three folds in Caco-2 cancer cells (0.22 ± 0.0008 for HepG2 and 0.32 ± 0.018 for Caco-2, respectively)." (PMID 36882428, 2023). "Apart from Raf and MEK, PKCγ can interact with ERKthat triggers cancer cells proliferation through cyclin D1.In cancer, SOCS3 acts as a suppressor." (PMID 37344815, 2023). "CCND1, a nuclear protein that regulates cell cycle and controls the G1‐S transition, is closely related to the occurrence and development of various cancers." (PMID 36915230, 2023). "Cyclin D1 is a key element of the cell cycle progression trigger in the cell which is abnormally expressed in various human cancers." (PMID 37686289, 2023). "Activated NF-κB signalling in cancer transactivates the expression of cyclin D1 and c-myc that promote cancer cell proliferation." (PMID 36899924, 2023). "KLF6 also inhibits cancer cell proliferation through p21-mediated cyclin D1/CDK4 expression, but this pathway is regulated by miR-181a." (PMID 36761967, 2023). "In the current study we found that silencing of these ubiquitin ligases resulted in increased stability and accumulation of cyclin D1 in human cancer cells leading to the stimulation of cell cycle progression." (PMID 37943017, 2023). "Cyclin D1, along with its main partner cyclin-dependent kinase 4 (Cdk4), is a pivotal cell cycle regulator and driver oncogene that is overexpressed in many cancers." (PMID 38152849, 2023). "Previous studies reported that aspirin suppressed the expression levels of c-Myc and Cyclin D1 in many cancer cells and also suppressed cell proliferation-related marker proteins, such as Ki67 and PCNA26–28." (PMID 38072949, 2023). "A recent meta-analysis of 108 original studies revealed that cyclin D1 had varying effects on prognosis, depending on the cancer site." (PMID 37894399, 2023). "In particular, the dysregulation of ubiquitination-dependent degradation of cyclin D1 contributes to not only the pathogenesis of malignancies but also the refractory to cancer treatment regiments with CDK4/6 inhibitors." (PMID 37414783, 2023). "KLF5 promotes the expression of E2F1, cyclin D1, and Rad51 in pancreatic cancer and assists in the G1/S phase progression of cancer cells." (PMID 36761967, 2023). "Expressions of Wnt1, β‐catenin and cyclin D1 at the protein level in NSCLC cells increased the risk of mutagenesis, increased cancer cell viability and decreased apoptosis." (PMID 37697969, 2023). "In a word, ASO is an effective strategy to correct the expression of cancer-related CCND1 isoforms through redirection of splicing and rebalancing the ratio of CCND1a/CCND1b." (PMID 37024471, 2023). "Previous studies have also reported that ferulic acid inhibits the expression of cyclin D1, reducing cell growth, and rescuing the expression of cyclin D1 in various cancer types." (PMID 37465088, 2023). "Mechanistically, MG53 promotes the ubiquitination-dependent degradation of cyclin D1 via functioning as its E3 ligase, leading to G1 arrest in the cyclin D1-dependent cancer cells." (PMID 37414783, 2023). "Blue light irradiation increased the expression of ki-67 and cyclin D1, which are indicators of cancer cell proliferation." (PMID 37626816, 2023). "Genetic lesions, such as gene amplification or mutations, can only account for a portion of the cases for the abnormal up-regulation of cyclin D1 in these cancers." (PMID 37943017, 2023). "Cyclin D1 has been proven as an oncogenic factor since upregulation of cyclin D1 was related to poor cancer prognosis." (PMID 36741908, 2023). "Cyclin D1 is frequently overexpressed and amplified in various cancer types, such as breast, esophageal, and lung cancers, due to its role in mitogen-dependent cell cycle control." (PMID 37669923, 2023).
cancer (continued). "In human cancer cell lines, cyclin D1 dysregulation contributes to cancer development via its interactions with more than 100 proteins." (PMID 37427143, 2023). "The overexpression of cyclin D1 in human cancers can result from genetic alterations, changes in epigenetic regulation, gene transcription, and protein translation of CCND1." (PMID 36975440, 2023). "Elevated expression of CLRN1-AS1 alleviates cancer progression by repressing the canonical Wnt signaling and downregulating cyclin D1, c-myc, beclin, and β-catenin." (PMID 38204968, 2023). "In this regard, formononetin has been shown to have a significant contribution in cancer inhibition through cell cycle arrest by affecting different cell cycle mediators, such as cyclin D1 and cyclin DK4 (CDK4)." (PMID 37298670, 2023). "Studies have shown that cyclin D1 is highly expressed in the mid-to-late G1 phase and exhibits an up-regulated kinase activity when bound to cdk4 in cancer cells." (PMID 37370134, 2023). "Studies have shown that BIRC6 can regulate the expression of cyclin D1, a vital regulator of the G1 phase of the cell cycle, in cancer cells." (PMID 38066801, 2023). "In this study, the combined morin/Dox treatment upregulated p21 and downregulated cyclin D1 protein levels, indicating increased DNA damage, cancer cell cycle arrest, and eventually cell death by altering the expressions of p21 and cyclin D1." (PMID 37242455, 2023). "Cyclin D1 has been recognized as an oncogene since it was upregulated in several different types of cancers." (PMID 37943017, 2023). "Cyclin D1, which is encoded by CCND1, is a critical regulator of the G1/S transition and promotes cancer progression in a complex with cyclin-dependent kinase (CDK) 4/6." (PMID 37894399, 2023). "Of note, abnormal regulation of the cell cycle is also a major feature of tumors, and knockdown of the ATAD2 gene leads to decreased expression of cyclin C and cyclin D1 in hepatocellular carcinoma, which is beneficial for cancer treatment." (PMID 36632213, 2023). "Cyclin D1 (CCND1) is one of the cell cycle regulators modulating the development of malignant tumours." (PMID 37935712, 2023). "Cyclin D1-expression is induced/deregulated in many malignant tumours due to a gene dosage effect by amplification of the cyclin D1-gene (CCND1), which is one of the most frequently amplified gene loci in solid cancers." (PMID 37509363, 2023). "The downregulation of the PI3K/AKT pathway by fucoidan contributed, in part, to a reduced expression of CDK-4, CDK-6, cyclin-E, and cyclin-D1, consequently halting cancer cell growth while inducing the apoptosis of the cancer cells." (PMID 38248653, 2023). "The importance and regulation of the CCND1 protein, cyclin D1, in cell proliferation and cancer has been thoroughly investigated." (PMID 36765275, 2023). "In colon cancer, IGF2BP3 increases the stability of CCND1 mRNA and promotes the proliferation of cancer cells." (PMID 37340423, 2023). "Due to the essential role of cyclin D1 in regulating transition from G1 to S phase in cell cycle, aberrant cyclin D1 expression is a major oncogenic event in many types of cancers." (PMID 37414783, 2023). "We explored the GSCA to determine the drug sensitivity profile data of c-Met/GSK3β/MYC/CCND1 against different cancer cell lines." (PMID 36672275, 2023). "Present study has unavoidable limitation of using four genes APP, CCND1, CCNE1, and PTPA only, since so far only four genes have been identified those are commonly implicated in cancer and neurodegeneration." (PMID 37383425, 2023). "MiR-27b-3p was also characterized as an oncogene in BC and CRC by enhancing cyclin D1 expression and thus promoting cell cycle progression and the proliferation of cancer cells." (PMID 36768818, 2023). "A large body of literature has shown that genetic alterations of CCND1 are extremely common in human cancers." (PMID 37024471, 2023).
cancer (continued). "The highly connected hub gene CCND1 encodes cyclin D1, which together with CDK4 and CDK6 kinases control G1 to S phase cell cycle progression and is frequently overexpressed in human cancers, promoting tumorigenesis." (PMID 37935712, 2023). "Deregulated cyclin D1 protein expression, gene translocation, and gene amplification are detected in many cancer types." (PMID 37190133, 2023). "Overall, the CCND1 gene appears to be a key player in drug resistance in cancer cells, representing a valuable target for the development of novel cancer treatments." (PMID 37744271, 2023). "ET-1 signaling target genes related to cancer progression include CCND1 (Cyclin-D1), AXIN2, PTGS2 (COX2), VEGF, ZEB1, and EDN1 (ET-1) itself." (PMID 38072958, 2023). "Cyclin D1 is an important player in cell cycle progression into the S phase, and c-Myc is a master regulator that is highly expressed in many types of cancer leading to an increase in the expression of many genes involved in cellular proliferation." (PMID 37064948, 2023). "Cyclin D1 upregulation has been observed in several cancers, leading to hyperproliferation with genomic instability." (PMID 37993427, 2023). "We chose CCND1 as a positive control, considering the substantial evidence supporting its role in cancer and the greater depth of CCND1 functional characterization compared with CCND2 and CCND3." (PMID 37081792, 2023). "Although Cyclin D1 plays a significant role in cancer, it is largely dispensable for normal physiology, as mice lacking CCND1 can survive with only minor developmental defects." (PMID 37669923, 2023). "Studies have shown that increased expression of CCND1 in cancer cells can lead to the activation of various drug-resistance pathways, such as the up-regulation of drug transporters and anti-apoptotic proteins." (PMID 37744271, 2023). "We revealed, for the first time in C4-2B cells, that PF-271 blocked FAK phosphorylation and increased FAK nuclear translocation, through which increased NR2F1 expression and inhibited cyclin D1 expression, in turn, induced cancer cell dormancy." (PMID 37821954, 2023). "Several studies have shown that carotenoids inhibit cancer cell proliferation by inhibiting the expression of cyclin D1, thereby preventing the progression of the G0/G1 cell cycle." (PMID 37761178, 2023). "In the future, we still need further investigation to fully clarify the role of the amplification and overexpression of CCND1 in cancers, and to make use of its prognosis and predict the value of biomarkers." (PMID 37024471, 2023). "A few studies have noted a relationship between the cyclin D1 expression and the response to cancer therapy." (PMID 37894399, 2023). "Accumulating results from cyclin D1 IHC studies in various carcinomas based on ROC analysis can help establish clear and consistent criteria for assessing cyclin D1 expression in the future." (PMID 37894399, 2023). "In carcinoma, 11q, 4q, and 8p alterations, cyclin D1 (CCND1) amplification, and phosphatase and tensin homolog (PTEN) inactivation are frequent." (PMID 38001610, 2023). "SHetA2 treatment reduced cyclin D1 levels and induced G1 cell cycle arrest in both cancer and healthy cells, although the extents were greater in cancer over healthy cells." (PMID 35281109, 2022). "The relative expression of Bax, Bcl-2, CCND1, and P21 genes that are involved in cancer was evaluated in this study." (PMID 35879795, 2022). "The decreased expression of IkBα was not able to inhibit NF-kB signaling pathway, promoting the expression of the downstream targets c-myc and Cyclin D1, the two of which were involved in the regulation of stemness of cancer cells." (PMID 36273585, 2022). "Cyclin D1 plays a vital role in cancer pathogenesis as its upregulated expression drives unchecked cellular proliferation." (PMID 35789645, 2022). "Both cyclin D1 and cyclin D3 are frequently upregulated in various cancers and their aberrant expression is well documented in promoting oncogenesis." (PMID 35406445, 2022).
cancer (continued). "The last component, cyclin D1, is frequently dysregulated in many human cancers, acting as an allosteric modulator of cyclin-dependent kinase 4 and 6 (CDK4/CDK6) and regulating the transition of G1 to S phase." (PMID 35448172, 2022). "Several iron chelators were proved to be effective anti-cancer agents and potential therapeutic potions, leading to the ubiquitin-proteasome degradation of cyclin D1." (PMID 36059670, 2022). "For instance, the transcription of CCND1 has been described to be regulated by HMG box protein 1 in cancers." (PMID 35246017, 2022). "The bacteria can also prevent cancer by downregulating the nuclear factor-kappaB-dependent gene products, which regulate cell proliferation (Cox-2, cyclin D1) and survival (Bcl-2, Bcl-xL)." (PMID 35993063, 2022). "Cyclin D1 (CCND1) represents one of the most frequently amplified loci among all human cancer types and plays a key role in the transition of cells from the G1 to S phase." (PMID 35668070, 2022). "ZFP36-encoded protein, tristetraprolin (TTP), an RNA binding protein, plays an important role in cancer cell proliferation through destabilizing Cyclin D1 and E2F1 mRNA." (PMID 34983615, 2022). "To accomplish this aim, we assessed the role of EGFR and cyclin D1 according to the depth of invasion and cancer stage." (PMID 35723316, 2022). "Cyclins and cyclin-dependent kinases (CDKs) are major effectors of the cell cycle with key role in cancer where our data shows downregulation of key cell-cycle proteins such as cyclin D1 and Geminin and mRNA levels of CCNE1, CCNF, CDK1, CDK2 and CDK5." (PMID 35902556, 2022). "By decreasing cyclin D1, PPIs are expected to restore the Bax-Bcl2 balance and allow mitochondrial apoptosis upon exposure of cancer cells to ionizing radiation." (PMID 35992826, 2022). "Correlation analysis revealed a high degree of correlation between CCND1 and p65 expression in cancer tissues." (PMID 35246017, 2022). "Cyclin D1 has previously been used as a biomarker for cell proliferation and prognosis in various types of cancer as much as the Ki-67 proliferation index has." (PMID 35723316, 2022). "The protein expression of CCND1 in cancer tissues was assessed by immunohistochemistry, and the protein expression of CCND1 was found to be higher in cancer tissues with CCND1 overexpression." (PMID 35246017, 2022). "The abrogation of the G1/S checkpoint or upregulation of the D1-type cyclins (Cyclin D1, Ccnd1)/cyclin-dependent kinases (Cdk4) pathway provides an obvious advantage to cancer cells in terms of proliferation and survival." (PMID 35462890, 2022). "Cyclin D1 is encoded by the CCND1 gene and is a promoter of the cell cycle, which is involved in the tumorigenesis of many cancers." (PMID 35795002, 2022). "Cyclin D1 and Cyclin E are critical proteins that are responsible for cell proliferation in various cancers." (PMID 36262967, 2022). "Cyclin D1/CDK4/6 holoenzyme complex is stimulated by the mitotic signal cascade to accelerate the proliferation of cancer cells." (PMID 36294924, 2022). "At the molecular level, NOP2 interacts with the T-cell factor of the cyclin D1 promoter in cancer cells, recruiting telomerase RNA component elements and activating cyclin D1 transcription." (PMID 36360287, 2022). "FDLE arrested cancer cells at the G0/G1 phase by downregulating p-NF-κB, cyclin D1 and CDK4, while upregulating p21 in both normal growth and inflamed HCT-116 and HT-29 cells." (PMID 35681644, 2022). "CCND1 is dysregulated in many cancers, indicating mutation of IL22RA1 contributes to cancer development." (PMID 35874683, 2022). "MCM7 facilitates cancer procession through cyclin D1-dependent signaling and serves as a prognostic marker for patients with HCC." (PMID 35639708, 2022). "In the case of Cyclin D1, prior research has detected a substantial dysregulation of this marker in several types of cancer." (PMID 35743985, 2022).